PLAC1 (placenta associated 1)
Diseases named in the same sentence as PLAC1 in open-access papers (continued):
Sharing a sentence is not in itself a finding about the gene and the disease.
tumor (continued). "Interestingly, neutralization of CD4+ T cells in mice injected with Plac1‐OE cells reduced both tumor volume (p = 0.0493) and weight (p = 0.0479) to levels comparable to those in the Plac1‐NC group (both tumor volume and weight: ns between groups)." (PMID 40056047, 2025). "Further studies are needed to assess how PLAC1 influences tumor progression and whether targeting it can effectively modulate the tumor microenvironment." (PMID 40607388, 2025). "Plac1 has a “dual immunosuppressive function” on tumor microenvironment." (PMID 35814442, 2022). "We evaluated the role of PLAC1 in tumor cells using PLAC1 knockdown and cell signaling assays." (PMID 32499871, 2020). "Our rescue experiments further confirmed that PTEN could reverse the tumor cell metastasis and invasion induced by Plac1." (PMID 29704427, 2018). "Finally, considering the colocalization of Tregs and Plac1+ tumor cells, we wondered whether Tregs in turn affect malignant cells and which cell‐cell interaction molecules induce these effects." (PMID 40056047, 2025). "The administration of anti‐PD1 could alleviate Plac1‐NC‐induced tumor growth (p = 0.0011)." (PMID 40056047, 2025). "Moreover, whether the expression of Plac1 on tumor cells addresses impacts on the whole TME remains to be clarified." (PMID 40056047, 2025). "Interestingly, the prognostic relevance of PLAC1 expression appears to be highly tumor-specific." (PMID 40607388, 2025). "By intersecting upregulated genes (Plac1+ versus Plac1− malignant epithelial cells) identified in the “endocytosis” pathway from in‐house data and GSE103322, we obtained a list of genes that were associated with endocytosis and were specifically expressed in Plac1+ tumor cells." (PMID 40056047, 2025). "However, to date, the role of PLAC1 in this tumor-promoting pathway is not clearly understood." (PMID 32499871, 2020). "In addition, the effect of Plac1 on tumor progression in vivo and the correlation between its expression and clinical prognosis are completely unknown." (PMID 29704427, 2018). "We found that TGFB1/EGFR, LTA/LTBR, CD46/JAG1, and AREG/EGFR ligand‐receptor pairs were stronger in CD4+ T cell‐Plac1+ tumor cells than in CD4+ T cell‐Plac1− tumor cells, among which LTA/LTBR expression was highly specific for Tregs and Plac1+ cells." (PMID 40056047, 2025). "While the direct role of PLAC1 as an NKAR ligand remains to be fully validated, our findings underscore its impact on NK cell activation and tumor cell recognition." (PMID 40607388, 2025). "The expression of PLAC1 in patients with CRC acts on oncogene loci to achieve the regulation of tumor genes, and the more obvious the expression in patients with low tumor tissue differentiation, the more it can be regulated by PLAC1." (PMID 37568074, 2023). "We previously demonstrated that AKT activation mediates the downstream effects of PLAC1; however, the molecular mechanisms of PLAC1-induced AKT-mediated tumor-related processes are unclear." (PMID 32499871, 2020). "Our findings reveal that Plac1 regulates a chemokine and immune tolerogenic signaling network necessary for sustaining tumor growth, which suggests potential therapeutic strategies that could alter the tumor microenvironment to make it more amenable to therapy." (PMID 29632317, 2018). "The relevance of Plac1 to mammary tumorigenesis was first noted in MMTV-PPARd mice, where Plac1 was markedly upregulated at the onset and throughout tumor development." (PMID 29632317, 2018). "To further confirm that Plac1 promotes tumor cell invasion and metastasis through suppression of PTEN, we overexpressed PTEN in Plac1‐overexpressing cells, followed by transwell migration and Matrigel invasion assays." (PMID 29704427, 2018). "Especially noteworthy was the greater infiltration of CD8+ T cells into the tumor bed following SB25002 treatment, which was accompanied by increased macrophage and Treg cell infiltration, reduction of Plac1 and increased apoptosis." (PMID 29632317, 2018).
tumor (continued). "Western blot was used to demonstrate that Plac1 regulates the PTEN/AKT signaling pathway, which further regulates MMP2 and MMP9 to promote tumor cell invasion and metastasis." (PMID 29704427, 2018). "Plac1 appears to be responsible for upregulating the expression of MMP2 and MMP9, which degrade the extracellular matrix to promote tumor cell invasion and metastasis." (PMID 29704427, 2018). "In conclusion, our findings demonstrate that one of the CTA genes, Plac1, is specifically expressed in HNSCC tumor cells and this gene promotes tumor progression through a dual mechanism involving both the enhancement of PI3K/AKT pathway and the induction of Treg differentiation." (PMID 40056047, 2025). "PVR/TIGIT, NECTIN2/CD226, and FAM3C/PDCD1 were relatively more strongly expressed in Plac1+ epi‐CD4+ T cells than Plac1− epi‐CD4+ T cells and PVR was specific for Plac1+ tumor cells, which was subsequently validated in HNSCC cells in vitro and in the TMA cohort by mIF." (PMID 40056047, 2025). "PLAC1 was detected in 97% of tumor biopsies, but did not correlate quantitatively with serum levels." (PMID 29432428, 2018). "PLAC1 expression was also observed in non-BL tumor cell lines derived from breast, ovary, and prostate." (PMID 24912876, 2014). "The functional relationship between PLAC1 and NCOA3 as well as the correlation analysis of PLAC1 expression with various clinical parameters like tumor size, overall and disease-free survival as well as resistance to therapy will be subjects of further studies." (PMID 24304549, 2013). "PLAC1 is expressed in tumor tissues, but little or no expression in normal tissues." (PMID 37568074, 2023). "Hence, we designed a candidate vaccine as a fusion protein, containing PLAC1, which is expressed highly in several types of tumor tissues, but not in normal ones, except placenta and testis." (PMID 31952435, 2020). "We also found a significant reduction in the levels of tumor promoter GPs at the end of 4th week during 4-week intermittent fasting (POLK, CD109, CAMP, NIFK, SRGN), and 1 week after 4-week intermittent fasting (CAMP, PLAC1) compared with the levels before 4-week intermittent fasting." (PMID 33110154, 2020). "In general, the reason for the presence or absence of PLAC1 expression at all in a tumor is unknown." (PMID 23935632, 2013). "Finally, PLAC1 might play a primarily immunological role, contributing to tumor immunogenicity rather than directly driving oncogenic transformation." (PMID 40607388, 2025). "Although Plac1 reduced growth in vitro, the lack of sustained growth of EO771/shPlac1 cells in syngeneic mice suggested that interactions with the tumor microenvironment may have contributed to this effect." (PMID 29632317, 2018). "EO771 “knockdown” (KD) resulted in 50% reduction in proliferation in vitro and impaired tumor growth in syngeneic mice; however, tumor growth in SCID mice was equivalent to tumor cells expressing a non-silencing control RNA, suggesting that Plac1 regulated adaptive immunity." (PMID 29632317, 2018).
PLAC1 also shares sentences with these, for which no sentence is quoted: lung cancer (3 papers); adenocarcinoma (2); breast invasive carcinoma (2); head and neck cancer (2); colon adenocarcinoma (1); colorectal adenocarcinoma (1); endometrial endometrioid adenocarcinoma (1); endometrioid adenocarcinoma (1); esophageal squamous cell carcinoma (1); fibrocystic disease (1); lobular breast cancer (1); lung squamous cell carcinoma (1); metastatic disease (1); multiple myeloma (1); Obesity (1); oropharynx cancer (1); osteosarcoma (1); ovarian serous cystadenocarcinoma (1); pancreatic cancer (1); paraganglioma (1); pheochromocytoma (1); renal carcinoma (1); serous adenocarcinoma (1); serous ovarian carcinomas (1); serous ovarian tumors (1); thyroid carcinoma (1).